LINC00239 (long independently transcribed non-coding RNA 239)
Synonyms: C14orf72; NCRNA00239
Gene: Long non-coding RNA gene on chromosome 14 (101,730,437 to 101,732,534, forward strand). Ensembl gene ENSG00000258512.
Diseases named in the same sentence as LINC00239 in open-access papers:
LINC00239 is named in the same sentence as 10 diseases in open-access papers, as found by Europe PMC text mining. Sharing a sentence is not in itself a finding about the gene and the disease. The quoted sentences say what the papers report.
colorectal cancer (5 papers, 2022 to 2025). A primary or metastatic malignant neoplasm that affects the colon or rectum. "Long intergenic non-coding RNA 239 (Linc00239) acts as an oncogene in colorectal cancer (CRC), esophageal squamous cell carcinoma, and acute myeloid leukemia cells." (PMID 38850457, 2025). "First, overexpression of LINC00239 is correlated with poor colorectal cancer and esophageal squamous cell carcinoma prognoses." (PMID 39497054, 2024). "Abnormally high expression of LINC00239 predicts poorer survival and prognosis in colorectal cancer patients." (PMID 36038548, 2022). "Considering the recurrence and chemoresistance constitute the leading cause of death in colorectal cancer (CRC), ferroptosis induction may be a promising therapeutic strategy for CRC patients with low LINC00239 expression." (PMID 36038548, 2022).
acute myeloid leukemia (2 papers, 2022 to 2025). Acute myeloid leukemia (AML) is a group of neoplasms arising from precursor cells committed to the myeloid cell-line differentiation. "Linc00239 is also overexpressed in acute myeloid leukemia cells and promotes oncogenic behavior by regulating PI3K/AKT/mTOR signaling." (PMID 38850457, 2025). "Previous studies have revealed that LINC00239, which is 652 nt in length, is upregulated in acute myeloid leukemia (AML), hepatocellular carcinoma (HCC), and CRC." (PMID 36038548, 2022).
Cirrhosis (2 papers, 2020 to 2022). A chronic disorder of the liver in which liver tissue becomes scarred and is partially replaced by regenerative nodules and fibrotic tissue resulting in loss of liver function. "The LINC00239-based risk score model can predict the prognosis of HCC patients with cirrhosis." (PMID 35685867, 2022). "Univariate analysis identified the following 11 lncRNAs as significantly correlated with RFS of patients with cirrhosis: SH3RF3-AS1, AC104117.3, AC136475.3, LINC00239, MRPL23-AS1, LINC00494, LINC01970, MEG3, Z93930.3, MIR9-3HG and TRBV11-2." (PMID 32592379, 2020).
cancer (4 papers, 2023 to 2025). A tumor composed of atypical neoplastic, often pleomorphic cells that invade other tissues. "Decreasing LINC00239 expression using targeted siRNAs inhibited cell proliferation and migration of various cancer cell types." (PMID 39497054, 2024).
tumor (2 papers, 2022 to 2024). "The elevated LINC00239 expression was associated with worse tumor size and higher AJCC stage." (PMID 36038548, 2022). "LINC00239 is an abnormally highly expressed tumor-promoting factor in colorectal cancer tissues and promotes tumor development by decreasing erastin- and RSL3-induced ferroptosis." (PMID 38392340, 2024). "3D tumor spheroid experiments further validated the inhibitory ferroptotic effect of LINC00239, as indicated by lower numbers of dead cells in LINC00239-overexpressing HCT116 cells and higher numbers of dead cells in LINC00239-knockout SW620 cells stained with SYTOX Green." (PMID 36038548, 2022). "Concurrently, we elucidated the role of LINC00239 as a tumor-promoting factor in CRC through in vitro functional studies and in vivo tumor xenograft models." (PMID 36038548, 2022). "In contrast, a smaller tumor size and lighter tumor weight were observed with SW620-sg-00239#1 cells, further confirming the oncogenic role of LINC00239 in CRC." (PMID 36038548, 2022). "In contrast, smaller tumor sizes and lighter tumor weights were observed in HCT116-OE-LINC00239-Keap1 and HCT116-OE-LINC00239-sgNrf2#1 cells, further confirming that Keap1/Nrf2 signaling is involved in the ferroptosis-suppressing activity of LINC00239 in CRC development." (PMID 36038548, 2022).
LINC00239 also shares sentences with these, for which no sentence is quoted: esophageal squamous cell carcinoma (2 papers); hepatocellular carcinoma (2); Clear Cell Renal Cell Carcinoma (1); lung carcinoma (1); nasopharyngeal carcinoma (1).